USP26 (ubiquitin specific peptidase 26)
Description:
Deubiquitinase regulating several biological processes through the deubiquitination of components of these processes. Involved in somatic cell reprogramming through the 'Lys-48'-linked deubiquitination and stabilization of CBX4 and CBX6, two components of the polycomb-repressive complex 1 (PRC1). Also deubiquitinates and probably stabilizes the androgen receptor (AR), regulating the androgen receptor signaling pathway. May play a role in spermatogenesis.
Synonyms: SPGFX6
Tractability: PROTAC: ubiquitination databases record sites on it.
Gene: Protein-coding gene on chromosome X (133,023,168 to 133,097,109, reverse strand). Ensembl gene ENSG00000134588.
Subcellular location: Nucleus; Cytoplasm, cytoskeleton, flagellum axoneme
Subcellular location (Human Protein Atlas): Nucleoplasm; Cytosol
Pathways (Reactome):
Metabolism of proteins: Ub-specific processing proteases
Gene Ontology:
Molecular function: cysteine-type deubiquitinase activity; deubiquitinase activity; K48-linked deubiquitinase activity; protein binding
Biological process: negative regulation of proteasomal ubiquitin-dependent protein catabolic process; regulation of androgen receptor signaling pathway; spermatogenesis; G1/S transition of mitotic cell cycle; protein deubiquitination
Cellular component: nucleoplasm; nucleus; sperm flagellum
Homologues: Orthologues: chimpanzee USP26 (98% identical), macaque USP26 (92% identical). Paralogues in human: USP29 (47% identical), USP37 (43% identical), USP32 (15% identical), USP6 (12% identical), USP19 (12% identical), USP24 (12% identical), USP8 (12% identical), USP15 (12% identical), USP4 (12% identical), USP11 (12% identical), USP31 (11% identical), USP38 (11% identical), and 59 more.
Diseases named in the same sentence as USP26 in open-access papers:
USP26 is named in the same sentence as 35 diseases in open-access papers, as found by Europe PMC text mining. Sharing a sentence is not in itself a finding about the gene and the disease. The quoted sentences say what the papers report.
male infertility (12 papers, 2014 to 2025). The inability of the male to effect fertilization of an ovum after a specified period of unprotected intercourse. "A novel framshift mutation c.2195delT (p.Phe732Serfs*14) in USP26 gene was reported to be associated with male infertility in a Chinese patient with severe oligozoospermia." (PMID 32202304, 2020). "Our results will enrich the USP26 mutation database and provide a genetic basis for the etiological diagnosis of male infertility." (PMID 32202304, 2020). "Genes associated with male infertility, including USP26, were assessed by targeted exome sequencing." (PMID 32202304, 2020). "USP26 is associated with Sertoli cell‐only syndrome and male infertility in both European and Chinese men." (PMID 33448640, 2020). "Prior mutation screening of USP26 demonstrated an association with human male infertility and low testosterone production, but protein localization and expression in the human testis has not been characterized previously." (PMID 24922532, 2014). "Similarly, associations between USP26 mutations and male infertility have been found to be significant in Asian populations but not in European or American populations." (PMID 40585997, 2025). "Several studies have reported the association of USP26 with male infertility." (PMID 34202084, 2021). "Previous reports have identified up to 20 USP26 polymorphisms, mostly occurring in gene clusters, that may be associated with male infertility." (PMID 32202304, 2020). "In one of the most comprehensive single nucleotide polymorphism (SNP) studies based on a genome wide association study and published male infertility genes, 147 SNPs were evaluated and 14 had significant association with male infertility including USP26 (rs35397110)." (PMID 24922532, 2014). "Our group and others have described specific mutations in USP26 which are associated with male infertility; however the mechanism of how such mutations modulate testicular function is unknown." (PMID 24922532, 2014). "USP26 gene mutations could play crucial role human male infertility." (PMID 35397626, 2022). "This included Usp26 itself, Dazl, which encodes an RNA-binding protein that is essential for gametogenesis in both males and females, Usp9y, a Y-linked gene encoding a deubiquitylase associated with male infertility and Dppa3, a primordial germ cell (PGC)-specific protein." (PMID 35857630, 2022). "It has long been controversial whether USP26 variants are associated with human male infertility." (PMID 31551464, 2019). "It is clear that the relationship between USP26 and male infertility remains controversial and needs to be fully elucidated." (PMID 32202304, 2020). "Thus, the role of USP26 variants and Usp26 mutations as risk factors for male infertility remains controversial, and it is possible that other genetic factors may contribute in a cooperative manner to the phenotype of USP26 variants and Usp26 mutations in humans and mice." (PMID 31551464, 2019). "The role of USP26 in male infertility, hypogonadism, and androgen-dependent cancer requires additional study." (PMID 24922532, 2014). "USP26 is a novel candidate gene for male infertility with USP26 expression previously reported in murine spermatogonia (types A and B), Sertoli cells, and potentially embryonic stem cells." (PMID 24922532, 2014). "Several studies reported the presence of different polymorphisms in USP26 in patients with nonobstructive azoospermia or severe oligozoospermia, suggesting that alterations in USP26 might be involved in male infertility." (PMID 35091692, 2022). "However, there are also studies using enzymatic assays or meta-analyses that do not support a direct association between USP26 variants and male infertility." (PMID 34202084, 2021). "USP26/AR expression and interaction in spermatogenesis and androgen-dependent cancer warrants additional study and may prove useful in diagnosis and management of male infertility." (PMID 24922532, 2014).
male infertility (continued). "We have also identified putatively causal variants in seven genes validated as aetiological factors of male infertility, such as SPAG17, REC114, TERB1, DNAH6, ADGRG2, MAMLD1, and USP26." (PMID 39678461, 2024).
Azoospermia (7 papers, 2014 to 2025). Absence of any measurable level of sperm,whereby spermatozoa cannot be observed even after centrifugation of the semen pellet. "Previous studies have also associated USP26 mutations with maturation arrest as a testicular phenotype, though other sperm-related issues, such as azoospermia, oligozoospermia, and asthenoteratozoospermia, have also been documented." (PMID 39932629, 2025). "USP26 azoospermia variants result in amino acid substitutions largely clustered around a nuclear localization sequence (NLS) and within the USP catalytic domain, with one variant implicated in the disruption of catalytic activity." (PMID 35857630, 2022). "In this regard, USP26 variants are found in azoospermia patients, and RLIM variants cause TOKAS, which is characterized by syndromic features including urogenital abnormalities in affected males and fertility problems in carrier females." (PMID 35857630, 2022). "USP26 gene variants have been implicated in the azoospermia, such as that associated with sertoli-cell only syndrome." (PMID 35857630, 2022). "We therefore hypothesized that USP26 variants identified from azoospermia patients may also lead to deregulation of the RNF12-USP26 axis and gametogenesis gene expression." (PMID 35857630, 2022). "Furthermore, USP26 variants have been associated with azoospermia in various fertility disorders, including Sertoli-cell only syndrome." (PMID 35857630, 2022). "Of note, we found that WT hUSP26 was a relatively long-lived protein, whereas the hUSP26 L364F variant was rapidly degraded, suggesting that impaired stability may explain the reduced protein amounts observed for USP26 azoospermia variants." (PMID 35857630, 2022). "Taken together, our data indicate that the RNF12-USP26 axis promotes gametogenesis gene expression, and this is functionally disrupted by RLIM and USP26 variants associated with TOKAS and azoospermia, respectively." (PMID 35857630, 2022). "Expression of WT hUSP26 resulted in increased expression of Usp26, Usp9y, Dazl, and Dppa3, whereas induction of these genes by the azoospermia-associated USP26 L364F variant was not significantly different from control samples." (PMID 35857630, 2022). "Genetic polymorphisms further verified the association of USP26 with abnormal spermatogenesis, from Sertoli-cell-only syndrome to non-obstructive azoospermia or asthenoteratozoospermia." (PMID 34202084, 2021). "Previous studies on USP26 have mostly focused on patients with azoospermia and oligozoospermia." (PMID 32202304, 2020). "Finally, we showed that the RNF12-USP26 axis was disrupted by RLIM variants from TOKAS patients, whereas RNF12 stabilization and downstream transcriptional regulation was disrupted by USP26 gene variants identified from azoospermia patients." (PMID 35857630, 2022). "In prior work by our group, sequence alterations in the USP26 gene were identified in approximately 11% of patients with severe oligospermia and non-obstructive azoospermia but were not identified in fertile controls." (PMID 24922532, 2014).
infertile (7 papers, 2014 to 2023). "A 370-371insACA, 494T>C, and 1423C>T gene cluster mutation in USP26 is most commonly reported in infertile male patients." (PMID 32202304, 2020). "Our mutation screening revealed that USP26 mutation is associated with infertility and low testosterone levels." (PMID 24922532, 2014). "Within human testis, USP26 was expressed in Leydig cells and early spermatogonia, as expected from our previously published mutational analysis showing USP26 mutations associated with infertility and low testosterone in men and our murine studies (not shown)." (PMID 24922532, 2014). "As a member of the USP family, numerous nucleotide variations in USP26 have been identified in infertile men." (PMID 34202084, 2021). "Furthermore, this RNF12-USP26 axis was disrupted by RLIM and USP26 variants found in TOKAS and infertility patients, respectively." (PMID 35857630, 2022). "USP26 is specifically expressed in testis tissue and is a potential infertility gene." (PMID 32202304, 2020). "The mutations at the SNPs of TEX11 (rs4844247), LHB (rs4146251380), USP26 (rs61741870) and (rs41299088), and ANOS1 (rs2229013) were displayed in only one of eight infertile men." (PMID 37895049, 2023).
breast carcinoma (5 papers, 2014 to 2025). "Specifically, normal human testis tissue demonstrates expression of USP26 between 20 and 1000 fold of the expression in thyroid cancer and at least 3 fold greater than breast cancer tissue." (PMID 24922532, 2014). "This may be explained by fact that only hormone dependent breast cancer overexpressed USP26 in microarray experiments." (PMID 24922532, 2014). "Breast cancer tissue may either overexpress or underexpress USP26." (PMID 24922532, 2014). "USP26 regulates SMAD7 stability, by deubiquitinating SMAD7, mitigating TGF-β1-induced migration and invasion in breast carcinoma cell lines." (PMID 29799477, 2018). "Novel regulators of SMAD7, including OTU domain- containing protein 1 (OTUD1) and ubiquitin-specific protease 26 (USP26), attenuate TGF-β1-mediated aggressive phenotypes in breast cancer." (PMID 29799477, 2018). "Having shown that USP26 is induced by RAC1B and that its knockdown decreased SMAD7 protein abundance, it remains to be determined whether in pancreatic carcinoma cells USP26 indeed binds to and deubiquitinates SMAD7 in breast cancer and glioma cells." (PMID 32545415, 2020).
Sertoli Cell-Only Syndrome (5 papers, 2014 to 2025). A type of male infertility in which no germ cells are visible in any of the biopsied SEMINIFEROUS TUBULES (type I) or in which germ cells are present in a minority of tubules (type II). "Stouffs and colleagues identified the presence of USP26 mutations in patients with various histological patterns of spermatogenic defects (Sertoli-cell-only syndrome and maturation arrest)." (PMID 34202084, 2021). "Mutations in the USP26 gene in Xq28 (also considered to be subject to positive selection pressure) were found in 7% of a series of patients with Sertoli cell-only syndrome." (PMID 25780578, 2014). "One patient with a USP26 mutation had Sertoli cell-only syndrome (SCOS) and no sperm, while another exhibited normal spermatogenesis with successful sperm retrieval, and a third showed post-meiotic arrest (PoMA) with sperm retrieved via TESE." (PMID 39932629, 2025).
esophageal squamous cell carcinoma (4 papers, 2022 to 2025). Esophageal squamous cell carcinoma (ESCC) is a type of esophageal carcinoma (EC) that can affect any part of the esophagus, but is usually located in the upper or middle third. "USP26 is highly expressed in esophageal squamous cell carcinoma (ESCC), which acts as a specific deubiquitinase of Snail and promotes ESCC cell migration and invasion." (PMID 35397626, 2022). "In addition, USP26 promotes esophageal squamous cell carcinoma metastasis by stabilizing Snail." (PMID 35091692, 2022). "In esophageal squamous cell carcinoma (ESCC), DUBs such as USP26 and OTUB1 are significant regulators of the EMT, a process crucial for cancer metastasis driven by the transcription factor Snail." (PMID 39678489, 2024). "Furthermore, USP26 108, PSMD14 121, OTUB1 117, and EIF3H 119 deubiquitinate and stabilize Snail, enhancing esophageal squamous cell carcinoma (ESCC) cell migration and tumor metastasis in vivo and in vitro." (PMID 41208892, 2025).
glioblastoma (4 papers, 2020 to 2025). The most malignant astrocytic tumor (WHO grade IV). "USP26 acts as a negative regulator of the TGF-β pathway, which suggests that loss of USP26 expression correlates with high TGF-β activity and poor prognosis in glioblastoma." (PMID 33158118, 2020).
prostate carcinoma (4 papers, 2015 to 2021). A carcinoma that arises from epithelial cells of the prostate gland. "Investigation of the effects of USP26 in prostate cancer is necessary given its role in activity and stability of the androgen receptor and the role of the androgen receptor in prostate cancer." (PMID 25605410, 2015). "It consists of three members, USP26, USP29 and USP37, of which USP26 is a positive regulator of Androgen Receptor in prostate cancer cells, USP37 directly deubiquitinates and stabilizes c-Myc in lung cancer, and USP29 has been recognized as a regulator of the checkpoint adaptor Claspin." (PMID 34272356, 2021). "In prostate cancer, USP14, USP22, and USP26 were reported to play roles in cancer progression." (PMID 34545063, 2021).
fertility disorders (2 papers, 2022 to 2024). "For example, mutations in the Usp26 gene caused sterility or subfertility in mutant males backcrossed on a DBA/2 background but not on a C57BL/6 background." (PMID 39231187, 2024).
Klinefelter syndrome (2 papers, 2023 to 2025). A sex chromosome disorder caused by the presence of an extra X chromosome in the male karyotype. "Another study demonstrated that the mutation of paternal Usp26 (ubiquitin-specific peptidase 26) increased the risk of having children with Klinefelter syndrome." (PMID 38169827, 2023). "The study demonstrated that variants in USP26 are associated with fathering of children with Klinefelter syndrome, suggesting that there could be a genetic cause for fathering children with sex chromosome aneuploidies." (PMID 39658337, 2025). "However, rare, deleterious variants in USP26 are increased in fathers of patients with Klinefelter’s syndrome." (PMID 39658337, 2025).
osteoarthritis (2 papers, 2023 to 2026). A noninflammatory degenerative joint disease occurring chiefly in older persons, characterized by degeneration of the articular cartilage, hypertrophy of bone at the margins and changes in the synovial membrane. "Identifying USP26 as a potential therapeutic target for physiological skeletal growth, bone fracture healing, and osteoarthritis." (PMID 41957346, 2026). "In addition, this study showed that depletion of USP26 impaired MSC chondrogenesis, suggesting that USP26 may be involved in osteoarthritis (OA) development." (PMID 36883930, 2023).
thyroid cancer (2 papers, 2014 to 2022). "Immunohistochemistry staining showed that the USP26 protein level was much higher in thyroid cancer samples than the normal tissues, indicating an oncogenic role of USP26 in thyroid cancer." (PMID 35397626, 2022). "USP26 was especially overexpressed in thyroid cancer as compared to normal thyroid." (PMID 24922532, 2014). "With mRNA and protein expression of USP26 confirmed in breast and thyroid cancer, the interaction of USP26 and AR may play a significant role in tumorigenesis." (PMID 24922532, 2014). "To further study the relationship of USP26 and TAZ in thyroid cancer, we examined the expression of USP26 and TAZ in thyroid cancer tissues and normal tissues." (PMID 35397626, 2022). "In addition, there was a significant positive correlation between USP26 and TAZ protein level in both thyroid cancer tissues." (PMID 35397626, 2022).
cervical cancer (1 paper, 2014). A primary or metastatic malignant neoplasm involving the cervix. "Expression in cervix and cervical cancer is very highly consistent with high expression levels of USP26 in HeLa cells." (PMID 24922532, 2014).
germ cell tumor (1 paper, 2014). A benign or malignant, gonadal or extragonadal neoplasm that originates from germ cells. "Study of various types of testicular histologies (SCO, MA, HS, seminoma, nonseminomatous germ cell tumor) for USP26 and AR expression is required." (PMID 24922532, 2014).
non-small cell lung carcinoma (1 paper, 2023). A group of at least three distinct histological types of lung cancer, including non-small cell squamous cell carcinoma, adenocarcinoma, and large cell carcinoma. "In pancreatic cancer and non-small cell lung cancer (NSCLC), various DUBs have also been found to be highly expressed, including OTUD3, USP5, USP17, USP21, USP26, and USP28, which usually predicts dismal prognostic outcome." (PMID 37251574, 2023).
osteoporosis (1 paper, 2022). A condition of reduced bone mass, with decreased cortical thickness and a decrease in the number and size of the trabeculae of cancellous bone (but normal chemical composition), resulting in increased fracture incidence. "Our data show the osteoprotective effect of USP26 via the coordination of bone formation and resorption and suggest that USP26 represents a novel therapeutic target for osteoporosis." (PMID 35091692, 2022). "Taken together, these data show the osteoprotective effect of USP26 via the coordination of bone formation and resorption, suggesting that USP26 represents a potential therapeutic target for osteoporosis." (PMID 35091692, 2022).
ovarian carcinoma (1 paper, 2014). A malignant neoplasm originating from the surface ovarian epithelium. "Thyroid, adrenal, and stomach cancer highly overexpress USP26, while prostate, and ovarian cancers have lower expression of USP26." (PMID 24922532, 2014).
rhabdomyosarcoma (1 paper, 2024). A rare aggressive malignant mesenchymal neoplasm arising from skeletal muscle. "The present study demonstrates that EV71 upregulates the expression of USP26 in human rhabdomyosarcoma cells (RD), suggesting a potential role for USP26 in regulating viral infections." (PMID 39058724, 2024).
testicular cancer (1 paper, 2014). A primary or metastatic malignant neoplasm that affects the testis. "Abnormal semen parameters associated with testicular cancer have been well documented and supports further study of USP26 in testicular cancer models." (PMID 24922532, 2014). "The relationship between USP26 and AR in testicular cancer requires further study." (PMID 24922532, 2014).